CPB2 (carboxypeptidase B2)
Diseases named in the same sentence as CPB2 in open-access papers:
CPB2 is named in the same sentence as 74 diseases in open-access papers, as found by Europe PMC text mining. Sharing a sentence is not in itself a finding about the gene and the disease. The quoted sentences say what the papers report.
COVID-19 (6 papers, 2021 to 2025). A disease caused by infection with severe acute respiratory syndrome coronavirus 2. "Earlier, in unrelated research, we have used DBK to monitor the serum activity of ACE and basic carboxypeptidases N and B2 (CPN, CPB2) in two clinical studies on Complex-Regional Pain Syndrome and COVID-19." (PMID 40572588, 2025). "In our study, CPB2 was overrepresented in all but asymptomatic COVID-19 patients, thus providing a candidate biomarker for disease severity." (PMID 34566994, 2021). "We observed reduced CPB2 levels in IVIG-treated patients relative to COVID-19 controls." (PMID 40821834, 2025). "Conversely, components of the coagulation cascade (SERPINA5, SERPIND1, PROC, CPB2, F13B, and KLKB1) and proteins involved in cholesterol metabolism were downregulated with the severity of COVID-19 but increased over time." (PMID 35958562, 2022).
enteritis (6 papers, 2016 to 2025). Inflammation of the small intestine. "In particular, extensive investigations of cpb2 and NetB genes, which are the major causes of enteritis, irrespective of the type of C. perfringens, are further required." (PMID 31434197, 2019). "Therefore, the cpb2 genes in CP280 may have been involved in the blood-like intestinal contents in the present case, and CP280 may also have the potential to cause enteritis in piglets, although further study is needed to test these hypotheses." (PMID 40458709, 2025). "Especially in piglets, a strong correlation between the prevalence of cpb2 in isolates from piglets with enteritis and the absence of cpb2 in isolates from healthy piglets was reported." (PMID 40458709, 2025). "It is possible that neither cpa nor cpb2 are key virulence factors in Type A. C. perfringens and that other unidentified virulence factors played a role in lorikeet enteritis." (PMID 35000619, 2022). "Moreover, even if both cpb-2 and netB toxin genes were present at relatively high frequencies in healthy farms at the start of the experiment, no clinical necrotic enteritis outbreak was observed throughout the duration of the study in these farms." (PMID 28567032, 2017).
breast carcinoma (4 papers, 2016 to 2024). "Expression of CPB2 (the gene encoding TAFI) was assessed in various breast cancer cell lines, using qRT-PCR." (PMID 27221823, 2016). "Moreover, a common single nucleotide polymorphism in CPB2 encoding a more stable TAFIa species was also more frequent in breast cancer patients than controls." (PMID 27221823, 2016). "Conversely, it has been reported that downregulation of CPB2 expression by siRNA reduces breast cancer cell proliferation, migration, and invasion." (PMID 36072669, 2022). "At the same time, previous research in cell line models has demonstrated that CPB2 results in the suppression of breast cancer cell invasion and migration, which is consistent with our findings." (PMID 36072669, 2022). "CPB2 mRNA was detectable in all of the examined breast cancer cell lines, albeit at a lower level in all cases compared to the positive control THP-1 macrophages, which is correspondingly much lower than reported in liver or a cultured hepatoma cell line." (PMID 27221823, 2016). "Moreover, carboxypeptidase B2 has been recognized as a central protein in the plasma of breast cancer patients, and its suppression by siRNA has been shown to impede the invasion and migration of breast cancer cells, suggesting its potential as a therapeutic target." (PMID 39204193, 2024). "Notably, in breast cancer, CPB2 expression is positively correlated with lymphovascular invasion." (PMID 39382373, 2024). "Therefore, levels of CPB2 mRNA do not appear to show any relationship to the malignancy of the breast cancer cell lines." (PMID 27221823, 2016).
diarrhoea (3 papers, 2017 to 2024). "This study aimed to assess and compare the efficacy of two commercial vaccination schemes under field conditions on a commercial farm where a C. perfringens type A cpb2-positive strain was implicated in neonatal piglet diarrhoea." (PMID 39460351, 2024). "This study aimed to assess and compare the efficacy of two commercial vaccination schemes under field conditions on a commercial farm, where a Clostridium perfringens type A cpb2-positive strain was implicated in neonatal diarrhoea in piglets." (PMID 39460351, 2024). "The presence of the cpb2 gene in 20.63% of isolates raises concerns of a potential threat to food safety, as this gene is implicated with aggravating gastro-intestinal symptoms in clinical cases linked to antibiotic-associated and sporadic diarrhoea." (PMID 38002242, 2023). "The information concerning the in vitro cytotoxicity of CPB2 and its involvement in the development of diarrhoea is quite controversial." (PMID 28545467, 2017). "However, other studies have found no apparent connection between C. perfringens type A cpb2-positive strains and neonatal diarrhoea in piglets." (PMID 39460351, 2024).
Venous thrombosis (3 papers, 2017 to 2024). Formation of a blood clot (thrombus) inside a vein, causing the obstruction of blood flow. "Although, most individual studies were unable to detect an association between CPB2 variants and the risk of thrombotic events, this meta-analysis supports the role of CPB2 variants in the risk of venous thrombosis." (PMID 28552956, 2017). "For example, VEGF c.-94C>T in chronic immune-mediated inflammatory disease functions as a protective factor in Asian populations and a risk factor in Caucasian populations, or CPB2 c.505G>A in venous thrombosis functions as a risk factor in Asians and a protective factor in Caucasian populations." (PMID 36293671, 2022). "A sex-specific effect was suggested in coronary heart disease for the Ala147Thr variant, in the CPB2 gene encoding TAFI, but sex effect on venous thrombosis remains to be determined." (PMID 28552956, 2017). "In total, the meta-analysis for the CPB2 Ala147Thr variant and venous thrombosis included a total of 8076 cases and 12 772 non-cases." (PMID 28552956, 2017).
autism (2 papers, 2019 to 2024). Persistent deficits in social interaction and communication and interaction as well as a markedly restricted repertoire of activity and interest as well as repetitive patterns of behavior. "It has been found that the expression level of the cpb2 gene is significantly higher in children with autism compared to normal children." (PMID 38971814, 2024). "In humans, cpb2 was detected in food poisoning cases as well as healthy individuals, and also in children with autism at a higher rate than control children." (PMID 31174364, 2019).
gas gangrene (2 papers, 2016 to 2021). A severe condition resulting from bacteria invading healthy muscle from adjacent traumatized muscle or soft tissue. "Comparative analysis showed that ~21 kb of pJFP55H (37% of plasmid length) has 74% sequence homology with a ~55 kb CPB2-encoding plasmid, pCP13, found in a type A C. perfringens that causes gas gangrene (Strain 13)." (PMID 26859667, 2016).
Insulin resistance (2 papers, 2021). Increased resistance towards insulin, that is, diminished effectiveness of insulin in reducing blood glucose levels. "While the inhibition of carboxypeptidase M in rats reverses insulin resistance, and cross-talk between carboxypeptidase N and Carboxypeptidase B2 is observed during complement activation, the functional relevance of the downregulation of this protein with ALT is unknown." (PMID 34203471, 2021).
Thromboembolic Disease (2 papers, 2021). "CPB2 is involved in the clotting-fibrinolytic pathway, and abnormal expression of this protein has been linked to thromboembolism and cancer." (PMID 34621695, 2021). "Consequently, numerous studies aimed at evaluating the association between proCPU levels and thromboembolic diseases and investigating the role of CPB2 SNPs as a risk factor." (PMID 33477318, 2021). "Furthermore, previous research has shown that single nucleotide polymorphisms (SNPs) in the CPB2 gene contribute to plasma proCPU concentrations, leading to the hypothesis that some of these proCPU variants might also contribute to a higher risk for thromboembolic diseases." (PMID 33477318, 2021).
autoimmune disease (1 paper, 2024). A disorder resulting from loss of function or tissue destruction of an organ or multiple organs, arising from humoral or cellular immune responses of the individual to their own tissue constituents. "The significant connection between the detection of the Cpb2 toxin-encoding gene and the presence of diabetes and autoimmune diseases (adjusted OR 27.52; 95% CI 1.68–50.67) suggests possible interactions between the microorganism and the host immune system." (PMID 38965598, 2024). "Notably, a strong association was found between the detection of the cpb2 gene and diabetes and autoimmune diseases (adjusted OR 27.52: 95% IC 1.68–50.67)." (PMID 38965598, 2024).
bacterial sepsis (1 paper, 2018). "Elevated levels of CPB2 have been found both in animal models of bacterial sepsis and in septic patients and have been hypothesized to play a role in the hypercoagulability associated with sepsis (24, –, 26)." (PMID 29950379, 2018).
C. perfringens infection (1 paper, 2022). "In the present research, we found that miR-30d expression decreased after CPB2 toxin treatment of the IPEC-J2 cells, and the expression was lowest at 36 h, which further indicated that miR-30d refers to regulate the process of C. perfringens infection in the piglets." (PMID 35799836, 2022).
cerebral aneurysm (1 paper, 2023). "The carboxypeptidase B2 (CPB2) showed a nominally negative association (P < 0.05) with the risk of neurological disorders including cerebral aneurysm and epilepsy." (PMID 36797296, 2023).
dermatitis (1 paper, 2024). An inflammatory process affecting the skin. "Thermal treatment of samples also inhibited the expression of serpin—with the exception of samples derived from donors with lichen planus—and CPB2 in supernatants from patients with psoriasis and dermatitis." (PMID 39062477, 2024).
endometrial cancer (1 paper, 2024). Primary or metastatic malignant neoplasm involving the endometrium (mucous membrane that lines the endometrial cavity). "For instance, microbial analysis of endometrium from patients with endometrial cancer and healthy volunteers revealed that Prevotella and Pelomonas were enriched in the endometrial cancer group, Prevotella was significantly associated with three genes (PRSS33, CPB2, XBP1)." (PMID 39360320, 2024).
endometrial tumor (1 paper, 2021). "Multiplex immunofluorescence confirmed that PRSS33, CPB2 and XBP1 proteins were significantly highly expressed in the endometrial tumor tissues of patients with elevated DD and FDPs, suggesting that Prevotella could partially promote DD and FDPs by influencing host gene expression." (PMID 34621695, 2021).
enterotoxemia (1 paper, 2017). Disease caused by the liberation of exotoxins of clostridium perfringens in the intestines of sheep, goats, cattle, foals, and piglets. "Out of 24 isolates from sheep suspected of enterotoxemia, 4 (16.66%) carried cpb2 while 2 (8.34%) were detected positive for cpe gene in toxinotype D. Among healthy sheep, 8 (9.30%) carried cpb2 while 1 (1.17%) isolate harbored cpe gene in toxinotype D out of 86 isolates (Table-4)." (PMID 29391693, 2017).
equine disease (1 paper, 2015). "Vilei and others demonstrated that some out-of-frame cpb2-positive equine disease isolates produced the CPB2 toxin when grown in sub-inhibitory concentrations of gentamicin." (PMID 25853427, 2015).
gastroenteritis (1 paper, 2019). An inflammatory disorder that affects the upper and lower gastrointestinal tract. "A total of 4 out of 109 outbreak-associated strains were cpe-negative, suggesting secondary virulence genes (e.g. pfo and cpb2) may be associated with C. perfringens-associated gastroenteritis." (PMID 31553300, 2019).
inflammatory breast carcinoma (1 paper, 2020). An advanced, invasive breast adenocarcinoma characterized by the presence of distinct changes in the overlying skin. "IL-10 stimulates the expression of carboxypeptidase B2 and promotes lymphovascular invasion in inflammatory breast cancer cell-line SUM-149, but not in non-inflammatory breast cancer cell MDA-MB-231." (PMID 33003428, 2020).
liver fibrosis (1 paper, 2022). "Our data agreed with those reported by Dai where FCN-2 and CPB2 proteins were shown as biomarkers of liver fibrosis through serum proteomics analysis and quantified using ELISA in a cohort of 46 CHB subjects." (PMID 35269955, 2022).
myocardial infarction (1 paper, 2019). Gross necrosis of the myocardium, as a result of interruption of the blood supply to the area, as in coronary thrombosis. "Increased expression of genes such as CPB2 was liable for advancement of myocardial infarction, but elevated expression of this gene may be associated with progression of CAD." (PMID 31881747, 2019).
non-small cell lung carcinoma (1 paper, 2025). A group of at least three distinct histological types of lung cancer, including non-small cell squamous cell carcinoma, adenocarcinoma, and large cell carcinoma. "In non-small cell lung cancer (NSCLC), the presence of BLV was significantly associated with PSG4 and CPB2 downregulation." (PMID 40143252, 2025).
ovarian tumor (1 paper, 2024). "However, the role of CPE and CPB2 in equine disease has not been established, as the application of CPE- and CPB2-producing isolates to an equine ovarian tumor cell line demonstrated diminished cytotoxicity compared to controls." (PMID 39453072, 2024).
pancreatitis (1 paper, 2023). Inflammation of the pancreas. "Individuals with hereditary pancreatitis associated with the pancreatitis susceptibility genes (PRSS1, CPA1, CPB2, and CTRC) have also been identified as HRIs, and surveillance for PC is recommended." (PMID 36766654, 2023). "In cases of CPA1 and CPB2 mutation associated with pancreatic cancer, the individuals do not have to progress through the clinical syndrome of pancreatitis." (PMID 36766654, 2023).
pneumococcal meningitis (1 paper, 2019). An acute purulent infection of the meninges and subarachnoid space caused by Streptococcus pneumoniae, most prevalent in children and adults over the age of 60. "A study with 716 pneumococcal meningitis patients studied the effect of polymorphisms in carboxypeptidase B2 (CPB2, rs1926447, rs3742264) on disease susceptibility and outcome." (PMID 31519222, 2019).
gastrointestinal disease (6 papers, 2006 to 2023). A disease that occurs in the gastrointestinal system, excluding the hepatobiliary system. "Meanwhile, it has been demonstrated that Beta2 toxin encoding cpb2 gene is associated with gastrointestinal diseases and significantly more common in the strains of Clostridium perfringens." (PMID 37925571, 2023). "Such a discrepancy in cytotoxicity of CPB2 was also previously reported in a study on the association of CPB2 and C. perfringens type A isolates carrying a plasmid enterotoxin gene in human gastrointestinal disease." (PMID 27672668, 2016). "The presence of the 28 kDa immune reactive band in the culture supernatant but not in the cellular extract of C. perfringens strains isolated from pigs with signs of gastrointestinal disease demonstrated that CPB2 was a secreted protein." (PMID 28545467, 2017). "Isolates originating from humans with gastrointestinal diseases, carrying both cpb2 and cpe, have been described recently." (PMID 16737528, 2006). "Isolates originating from humans with gastrointestinal diseases carrying both cpb2 and cpe have recently been described." (PMID 16737528, 2006). "The high prevalence of the cpb2 gene in isolates from pigs and horses is consistent with other studies reporting a high prevalence of cpb2 in pigs and horses suffering from gastrointestinal diseases." (PMID 16737528, 2006). "The presence of cpb2 gene is correlated with gastrointestinal diseases in humans and other animals." (PMID 35324837, 2022). "However, isolates containing cpb2 isolated from humans with a gastrointestinal disease were distributed in both groups (Ic and IIa), irrespective of origin." (PMID 16737528, 2006).
tumor (6 papers, 2011 to 2024). "The study revealed higher CPB2 expression in tumor tissue compared to normal mucosal tissue." (PMID 39382373, 2024). "Furthermore, tumors with high CPB2 expression have been related to more advanced tumor stages." (PMID 36072669, 2022).
intestinal diseases (5 papers, 2016 to 2022). "The involvement of CPB2 in intestinal diseases of different animal species also remains unproven, since cpb2-positive C. perfringens strains are commonly isolated from healthy animals." (PMID 33843463, 2021). "The results suggest that m6A methylation may play a role in the Wnt signaling pathway in CPB2-induced IPEC-J2 cells and exert anti-inflammatory or proinflammatory effects on intestinal diseases." (PMID 34737761, 2021).
cancer (3 papers, 2021 to 2024). A tumor composed of atypical neoplastic, often pleomorphic cells that invade other tissues. "Therefore, the CPB2 gene is worth exploring further to shed light on underlying mechanisms in cancer cells." (PMID 36072669, 2022). "In the study of KIRC cancer progression, CALCA and CPB2 were identified as genes that promote the deterioration process, and CALCA showed significant expression in stage TA and I samples, followed by a decrease in expression." (PMID 38459043, 2024). "CPB2 gene was differentially expressed in stages III and IV, which means that its expression may directly participate in cancer deterioration." (PMID 38459043, 2024).
infection (3 papers, 2016 to 2024). The state of being infected such as from the introduction of a foreign agent such as serum, vaccine, antigenic substance or organism. "Our results provide evidence that infection of birds with CP containing cpa+netB+tpeL+cpb2 genes can effectively dampen the proliferation Romboutsia and Lactobacillus and produce NE." (PMID 38243294, 2024).
cardiovascular disease (2 papers, 2017 to 2024). "Prior suggestions of sex differences in risk profiles for variants in the CPB2 gene for cardiovascular disease led to sex-specific analyses to detect associations that may otherwise be missed when both sexes are analyzed together." (PMID 28552956, 2017).
infectious disease (1 paper, 2023). A disorder directly resulting from the presence and activity of a microbial, viral, or parasitic agent in humans. "C. perfringens type C is a Gram-positive anaerobic bacterium that produces the extremely pathogenic CPB2 toxin, causing a variety of inflammatory reactions and infectious diseases." (PMID 36718447, 2023).
CPB2 also shares sentences with these, for which no sentence is quoted: ischemic stroke (3 papers); co-infection (2); Infertility (2); necrotizing enterocolitis (2); acromegaly (1); adenocarcinoma (1); angioedema (1); aortic stenosis (1); atherosclerosis (1); atrial fibrillation (1); colitis (1); complex regional pain syndrome (1); coronary heart disease (1); Cushing syndrome (1); dependence (1); diabetes (1); diabetic kidney disease (1); diarrheal disease (1); endometritis (1); enterocolitis (1); epilepsy (1); gangrene (1); hepatoma (1); Hypercalcemia (1); hypercoagulability (1); infectious diarrhea (1); interstitial lung disease (1); ischemia (1); lichen planus (1); lung adenocarcinoma (1).
A further 11 diseases each share a sentence with CPB2 in 1 paper.